ASPG (asparaginase)
Diseases named in the same sentence as ASPG in open-access papers (continued):
Sharing a sentence is not in itself a finding about the gene and the disease.
central nervous system leukemia (2 papers, 2018 to 2021). Leukemia infiltrating the central nervous system structures. "Also, intensive asparaginase treatment was important to control CNS leukemia." (PMID 33796456, 2021). "Therefore, the patient was considered as central nervous system leukemia (CNSL) and immediately received 2 courses of chemotherapy with hyper-CVAD-B combined with polyethylene glycol conjugated asparaginase (PEG-ASP)." (PMID 30407314, 2018).
gastric cancer (2 papers, 2025). A primary or metastatic malignant neoplasm involving the stomach. "This study unveiled genomic factors driving tumour metabolic reprogramming, including the amplification of the malic enzyme 2 and the proposed targeting of asparaginase metabolism in gastric cancer." (PMID 40136651, 2025).
hemorrhage (2 papers, 2020 to 2024). Loss of blood from the vascular compartment to the exterior or into nonvascular body space as a result of rupture or severance of the blood vessels. "We present the case of a 13-year-old boy with ALL who developed CVST and intrinsic hemorrhage approximately 30 days after receiving chemotherapy with vincristine, dexamethasone, daunorubicin, and pegylated-asparaginase (PEG-Asp)." (PMID 39318612, 2024).
liver cancer (2 papers, 2021 to 2023). An epithelial or non-epithelial malignant neoplasm that arises from the liver. "The results suggest that this purified T. viridel-asparaginase may be able to delay the development of liver cancer and may be used as a potential candidate for future application in medicine as an anticancer medication." (PMID 36995465, 2023). "In our study, it was found that ASRGL1 was highly expressed in liver cancer, which may play a role in promoting tumor development through the antagonism of asparaginase and lead to poor prognosis of patients." (PMID 34249720, 2021).
lung carcinoma (2 papers, 2017 to 2018). "The ATF4 modulation exerted by oncogenic KRAS is required for apoptosis suppression via control of asparaginase biosynthesis: inhibition of AKT suppresses asparaginase expression and, combined with low extracellular asparagine, decreased the growth of KRAS-mutant lung cancers." (PMID 30060526, 2018).
melanoma (2 papers, 2015 to 2022). A malignant, usually aggressive tumor composed of atypical, neoplastic melanocytes. "Asparaginase treatment would drive melanoma cells to increaseasparagine synthesis from aspartate and glutamine." (PMID 25749035, 2015).
mucositis (2 papers, 2017 to 2022). Mucositis is inflammation and damage of the mucous membranes lining the mouth and other parts of the gastrointestinal (GI) tract. "Grade 3/4 mucositis was more frequent in patients treated with CCRT-VIPD (66.7%) than CHOP-like regimens (6.3%), asparaginase-based regimens (32.3%) and others anti-MDR drug regimens (20.0%), p < 0.001." (PMID 36446856, 2022).
NK / T cell lymphoma (2 papers, 2020 to 2021). "Related studies have shown that the clinical efficacy of GemOx + asparaginase + dexamethasone Chemotherapy regimen in primary NK / T cell lymphoma patients, and its clinical efficiency can reach up to 91% (62% CR rate, 29% PR rate)." (PMID 31914048, 2020). "Two patients with extranodal NK/T cell lymphoma received methotrexate (3 g, day 1), heterocyclic phosphamide (3 g, day 2; 2 g, day 3–4), dexamethasone (40 mg, days 2–4), etoposide (100 mg, days 2–4), and asparaginase (10,000 U; days 8, 10, and 13) (SIMLE regimen)." (PMID 35154000, 2021).
Obesity (2 papers, 2021 to 2026). Accumulation of substantial excess body fat. "This has been demonstrated in mice, where obesity causes activation of maladaptive pathways in hepatocytes in response to asparaginase‐induced metabolic stress, leading to reduced ability of the cells to be rescued from this stress by normal pathways." (PMID 34528411, 2021). "Obesity is a known risk factor for asparaginase-associated liver steatosis." (PMID 41801222, 2026).
pancreatic adenocarcinoma (2 papers, 2020 to 2024). "A follow-on Phase IIb study evaluating erythrocyte-encapsulated asparaginase (relabeled as eryaspase) in combination with chemotherapy in second-line advanced pancreatic adenocarcinoma was conducted." (PMID 32397259, 2020). "Erythrocyte encapsulated asparaginase was subsequently extended to a Phase I clinical trial for the treatment of patients with pancreatic adenocarcinoma with null/low asparagine synthetase expression." (PMID 32397259, 2020).
renal cell carcinoma (2 papers, 2022 to 2024). "•Asparaginase alters DNA synthesis efficiency of a renal cell carcinoma cell line." (PMID 39170541, 2024). "•Asparaginase alters cell cycle of a renal cell carcinoma cell line." (PMID 39170541, 2024).
antithrombin deficiency (1 paper, 2017). "Chemotherapeutic agents are also highly thrombogenic, including asparaginase, which causes antithrombin deficiency and steroids which increase factor VIII/von Willebrand factor complex." (PMID 28168186, 2017).
Anxiety (1 paper, 2022). Intense feelings of nervousness, tension, or panic often arise in response to interpersonal stresses. "While the safety and efficacy of both asparaginase preparations was similar, there was significantly less anxiety associated with IV PEG administration, supporting its use over IM native E. coli asparaginase in the front-line setting." (PMID 35844739, 2022).
Autoimmunity (1 paper, 2025). The occurrence of an immune reaction against the organism's own cells or tissues. "Therapeutic Asn depletion by targeted asparaginase treatment may provide a conceptually novel strategy for autoimmunity." (PMID 40661510, 2025).
B-cell acute lymphoblastic leukemia (1 paper, 2024). A neoplasm of lymphoblasts committed to the B-cell lineage, typically composed of small to medium-sized blast cells. "Pegylated (PEG)-asparaginase is used during the induction and intensification phases of treatment for B-cell acute lymphoblastic leukemia (B-ALL)." (PMID 39011188, 2024).
brain tumors (1 paper, 2017). "Differential expression of ASNS in ependymomas and certain types of medulloblastomas also supports asparaginase testing against these pediatric brain tumors." (PMID 28245795, 2017).
cerebral thrombosis (1 paper, 2021). "The two cases of cerebral thrombosis, one venous and one arterial, occurred during induction and after the third and sixth doses of asparaginase, respectively." (PMID 34640436, 2021).
Cyanosis (1 paper, 2021). Bluish discoloration of the skin and mucosa due to poor circulation or inadequate oxygenation of arterial or capillary blood. "Norman found that 16 cases of asparaginase had two cases of cyanosis and choking episodes, and these side effects were generally mild." (PMID 34988029, 2021).
Encephalopathy (1 paper, 2024). Encephalopathy is a term that means brain disease, damage, or malfunction. "During the metabolic breakdown of asparaginase, aspartic acid and ammonia develop, which can be associated with encephalopathy but in the context of a previous liver lesion." (PMID 39857862, 2024).
glioblastoma (1 paper, 2017). The most malignant astrocytic tumor (WHO grade IV). "Herein, we investigated the mechanisms of how glioblastoma resisted asparaginase treatment and reported a novel approach to enhance the anti-glioblastoma effect of asparaginase." (PMID 29207624, 2017). "Moreover, combination treatment with autophagy inhibitor CQ significantly enhanced anti-glioblastoma efficacy of asparaginase in U87MG cell xenograft model." (PMID 29207624, 2017). "However, the anti-glioblastoma effect of asparaginase alone was moderate in vitro, and xenograft tumors in vivo showed no significant response to asparaginase monotherapy." (PMID 29207624, 2017). "Besides, previous studies mainly paid attention to synergistic cytotoxicity of asparaginase and other chemotherapeutics, and the underlying mechanism influencing the anti-glioblastoma effect of asparaginase has not been well elucidated." (PMID 29207624, 2017). "In addition, several literature has reported the anti-tumor effect of asparaginase on glioblastoma." (PMID 29207624, 2017). "Finally, to further evaluate the therapeutic efficacy of asparaginase and prove whether suppression of autophagy could potentiate the anti-glioblastoma effect of asparagine depletion in vivo, we established a tumor xenograft model using U87MG cell line." (PMID 29207624, 2017). "We found that asparaginase could induce growth inhibition and caspase-dependent apoptosis in U87MG/U251MG glioblastoma cells." (PMID 29207624, 2017). "Therefore, we highly speculated that asparaginase could trigger autophagy in GBM cells, and suppression of autophagy could potentiate the anti-tumor effect of asparagine depletion on glioblastoma." (PMID 29207624, 2017).
hypersensitivity reactions (1 paper, 2022). "However, the high incidence of hypersensitivity reactions (average 30%), which end up causing early treatment interruption, caused others types of asparaginase to replace native asparaginase in many countries." (PMID 34431241, 2022). "Therefore, once a hypersensitivity reaction is observed, treatment with asparaginase is definitely suspended." (PMID 34431241, 2022).
influenza infection (1 paper, 2024). "Removal of environmental Asn by asparaginase or dietary restriction compromised the GC reaction, impairing affinity maturation and the humoral response to influenza infection." (PMID 39671468, 2024).
Insulin resistance (1 paper, 2025). Increased resistance towards insulin, that is, diminished effectiveness of insulin in reducing blood glucose levels. "In this study, we found hepatic ASPG protein levels were positively associated with insulin resistance indexes in MAFLD patients." (PMID 40760121, 2025). "Insulin resistance and systemic glucose metabolism are controlled by non-canonical lysophospholipase activity of liver asparaginase, controlling hepatokine secretion." (PMID 40760121, 2025).
leukopenia (1 paper, 2021). "Ven-PegC caused leukopenia, a known adverse event of Ven but not asparaginase, with no other blood cell count changes." (PMID 33199836, 2021).
Lewis lung carcinoma (1 paper, 2022). "More recently, a similar effect of Asparaginase loaded in long circulating liposomes, by including DSPE-PEG in the lipid composition, improved the therapeutic effect, in a Lewis lung carcinoma murine model, to a higher extent in comparison to the enzyme in the free form." (PMID 35335906, 2022).
liver disease (1 paper, 2022). "Moreover, CG + GG genotypes were associated with an increased risk of toxic liver disease after treatment with asparaginase, cyclophosphamide, cytarabine, daunorubicin, mercaptopurine, prednisolone, and vincristine." (PMID 36233078, 2022).
liver fibrosis (1 paper, 2024). "Other liver fibrosis-associated amino acid pathways included asparaginase activity in stool and tryptophan-to-kynurenine conversion in the liver." (PMID 39239875, 2024).
malaria (1 paper, 2015). Malaria is a serious and sometimes fatal disease caused by a parasite that commonly infects a certain type of mosquito which feeds on humans. "Here we use P. berghei as an in vivo rodent parasite model to address the significance of asparagine requirement in the entire life cycle of malaria parasites by performing targeted deletion of endogenous AS and depleting the extracellular asparagine by asparaginase treatment." (PMID 26531182, 2015).
migraines (1 paper, 2019). "In humans, GRIA1 has been linked to the neurological disease schizophrenia, asparaginase hypersensitivity, and migraines." (PMID 30999842, 2019).
NK cell leukemia (1 paper, 2018). "The sensitivity of NK cell leukemia to asparaginase suggests that GCN2 may be a drug target in this cancer as well." (PMID 30364637, 2018).
pancreatic ductal adenocarcinoma (1 paper, 2022). An infiltrating adenocarcinoma that arises from the epithelial cells of the pancreas. "Low ASNS expression in tumor cells, including certain solid cancers, such as pancreatic ductal adenocarcinomas, could be used to suggest patients the treatment with asparaginase-added chemotherapy." (PMID 36405587, 2022). "Thus, asparaginase may be suggested as effective drug for the treatment of pancreatic ductal adenocarcinomas lacking ASNS expression." (PMID 36405587, 2022).
parasitemia (1 paper, 2013). "However, when induced T. brucei RNAi clones were injected in mice undergoing asparaginase treatment, which depletes blood asparagine, the mice exhibited lower parasitemia and a prolonged survival in comparison to similarly-treated mice infected with control parasites." (PMID 24340117, 2013).
polyneuropathy (1 paper, 2025). A disease or disorder affecting more than one nerve. "For cytarabine, cerebellar damage is characteristic; for asparaginase, thromboembolic incidents; and for vincristine, peripheral polyneuropathy." (PMID 40869695, 2025).
psychotic disorder (1 paper, 2024). An abnormal condition of the mind that involves a loss of contact with reality. "However, psychotic symptoms (e.g., delusions or hallucinations) may develop in cancer patients with no pre-existing psychotic disorder, secondary to CTx agents such as chlorambucil, hydroxyurea, ifosfamide, asparaginase, corticosteroids, interferon-alpha, interleukin-2, and procarbazine." (PMID 39614312, 2024).
pterygium (1 paper, 2024). A wedge-shaped fibrovascular lesion arising from the bulbar conjunctiva and extending to the cornea. "The SVM algorithm was also employed to rigorously select hub genes associated with pterygium, revealing five significant genes: KRT10, KRT6B, BTG2, ASPG and NGEF." (PMID 39722894, 2024).
ptosis (1 paper, 2025). The drooping of the upper eyelid. "On 14 February 2023, the patient was administered a regimen of high-dose methotrexate, asparaginase, and calcium folinate, which was well tolerated and resulted in regression of ptosis and a discrete improvement in exophthalmos." (PMID 39860409, 2025).
retinal degeneration (1 paper, 2022). Degeneration of the retina. "Earlier in vitro studies revealed a significant loss of asparaginase activity due to the G178R mutation that was detected in patients with retinal degeneration and suggested that appropriate retinal structure and function are dependent on ASRGL1 activity." (PMID 36011372, 2022).
Seizure (1 paper, 2024). A seizure is an intermittent abnormality of nervous system physiology characterized by a transient occurrence of signs and/or symptoms due to abnormal excessive or synchronous neuronal activity in the brain. "Seizures can be caused by MTX (such as transient stroke like syndrome) but also due to asparaginase treatment." (PMID 38285235, 2024).
Splenomegaly (1 paper, 2025). Abnormal increased size of the spleen. "Considering the small sample number of the entire cohort and the limited number of PD-1 antibody subgroup, LASSO model was used and identified five potential prognostic factors, including splenomegaly, subacute clinical course, HSCT, PD-1 antibodies and asparaginase." (PMID 40297575, 2025).
T-cell acute leukemia (1 paper, 2020). "In another example, a recent study used the GeCKO library to identify synthetic lethal interactions between asparaginase and Wnt signaling in asparaginase-resistant T-cell acute leukemia cell lines treated with either vehicle control or a high dose of asparaginase." (PMID 33120942, 2020).
urticaria (1 paper, 2021). A vascular reaction of the skin characterized by erythema and wheal formation due to localized increase of vascular permeability. "One relapsed ALL patient showed an extremely low AUC of asparaginase activity which coincided with urticaria after asparaginase injection." (PMID 34711008, 2021). "This case had also reported asparaginase clinical hyperreactivity as urticaria." (PMID 34711008, 2021).
cancer (75 papers, 2014 to 2025). A tumor composed of atypical neoplastic, often pleomorphic cells that invade other tissues. "For instance, increased expression of LCK, ITGA5, CGH1 and TNFRSF9 was associated with increased drug sensitivity of cancer cells to ribavirin, nelarabine, zalcitabine, bleomycin, asparaginase, dexrazoxane, palbociclib, etc." (PMID 38903179, 2024). "This overexpression of ASNS has been linked to a mechanism of resistance to asparaginase-based therapies, which are used to target asparagine in cancer treatment." (PMID 39795937, 2024). "Understanding the reasons behind the dual decline in asparagine and glutamine levels caused by asparaginase treatment is crucial for optimizing cancer treatment regimens involving asparaginase." (PMID 39050845, 2024). "CENPA expression was associated with higher drug resistance to nelarabine, asparaginase, dexamethasone Decadron, cladribine, and hydroxyurea in cancer cells." (PMID 36213834, 2022). "The main enzymes associated with cancer and anticancer include asparaginase, acyltransferase, α-glucosidase, α-amylase, β-glucosidase, β-glucuronidase, gelatinase, glutaminase, laccase, lactate dehydrogenase, triacylglycerol lipase, mono phenol mono-oxygenase, and xylan endo 1,3, β-xylosindase." (PMID 34070936, 2021). "The in vivo xenograft mouse model confirmed that ASPG-OE CAR-T cells exhibited superior anticancer activity against NALM6-GL cancer cells, while ASPG-KO CAR-T cells exhibited inferior anticancer activity." (PMID 40808257, 2025). "This underlines the critical role of asparagine in supporting cell proliferation, as it is targeted in cancer therapies using asparaginase." (PMID 41417254, 2025). "For example, GCN2 drives the expression of asparagine synthetase (ASNS) via eIF2a/ATF4, which is required for cancer cell survival upon asparaginase treatment." (PMID 39319345, 2024). "The phenomenon of concurrent decreases in asparagine and glutamine levels following asparaginase treatment, an interesting observation in our therapy studies, highlights the complex interplay of amino acid metabolism in cancer treatment." (PMID 39050845, 2024). "The compound effectively modulated ASNS expression and induced programmed cell death (apoptosis) in cancer cells, suggesting its potential as a therapeutic strategy in overcoming asparaginase resistance and selectively targeting cancer cells." (PMID 39795937, 2024). "Future research focusing on how asparaginase affects glutamine metabolism will provide deeper insights into cancer cell metabolic vulnerabilities, paving the way for developing new treatment strategies based on these metabolic dependencies." (PMID 39050845, 2024). "The inhibition of GSK3α halts the sourcing of amino acids, which subsequently leads to cancer cell vulnerability toward asparaginase therapy." (PMID 37686063, 2023). "Increased asparaginase activity in presence of calcium ions strongly favors the use of current enzyme in cancer therapy, as the cell proliferation and apoptosis of cancer cells is dependent on intracellular calcium concentration." (PMID 38015853, 2023). "The limitation of this treatment is the intolerant toxicity and therapy resistance, because cancer cells remain proliferative despite asparaginase treatment, the mechanism of which little is known." (PMID 36457557, 2022). "Treatment of cancer cells with asparaginase can be augmented by the inhibition of GCN2, which is a part of the integrated stress response that upregulates amino acid biosynthesis and transport." (PMID 36210829, 2022). "The results of immunohistochemistry (IHC) in the Human Protein Atlas (HPA) database showed that compared with normal tissues, ENOPH1, ACAT1, ALDH4A1, FAS, and ASPG are downregulated in cancer tissue than in normal tissue." (PMID 35992263, 2022). "As a result, the up-regulation of RNF144B predicted cancer cell resistance against docetaxel and asparaginase." (PMID 36497225, 2022).